ST6GAL1 (ST6 beta-galactoside alpha-2,6-sialyltransferase 1)
Description:
Transfers sialic acid from CMP-sialic acid to galactose-containing acceptor substrates. In B lymphocytes, generates neuraminidase-sensitive lymphocyte cell-surface differentiation antigens, such as CDw75, HB-6 and CD76. Sialylates complex-type N-glycans attached on the fragment crystallizable (Fc) of IgGs confering anti-inflammatory effector functions. Preferentially monosialylates the alpha(1->3) mannose antenna of Fc glycoforms with subsequent disialylation occurring at a much slower rate.
Synonyms: ST6GalI; SIAT1; CDw75; ST6N
Tractability: Small molecule: a structure with a bound ligand is known; a high-quality ligand is known. Antibody: UniProt places it where antibodies can reach, with medium confidence; UniProt predicts a signal peptide or a membrane-spanning region; its Gene Ontology location is reachable by antibodies, with medium confidence. PROTAC: ubiquitination databases record sites on it; its protein half-life has been measured; a small molecule that binds it is known.
Target class: Enzyme; Transferase
Gene: Protein-coding gene on chromosome 3 (186,930,325 to 187,078,932, forward strand). Ensembl gene ENSG00000073849.
Subcellular location: Golgi apparatus, Golgi stack membrane; Secreted
Pathways (Reactome):
Metabolism of proteins: N-Glycan antennae elongation; Sialic acid metabolism; Termination of O-glycan biosynthesis
Disease: Maturation of protein 3a; Maturation of spike protein
Gene Ontology:
Molecular function: beta-galactoside alpha-2,6-sialyltransferase activity; protein binding; protein homodimerization activity; sialyltransferase activity
Biological process: N-acetylneuraminate metabolic process; protein N-linked glycosylation; sialylation; protein O-linked glycosylation via N-acetyl-galactosamine; viral protein processing; glycoprotein biosynthetic process
Cellular component: Golgi membrane; extracellular region; Golgi apparatus; Golgi cisterna membrane
Genetic constraint (gnomAD): Loss-of-function variants: 19 observed, 38.02 expected, observed/expected ratio (o/e) 0.5, 90% interval 0.35 to 0.73. The upper end of that interval is the gene's LOEUF score, 0.73, which puts it in group 3 of 6, group 1 being the genes least tolerant of losing a copy. Missense variants: 430 observed, 515.92 expected, observed/expected ratio (o/e) 0.83, 90% interval 0.77 to 0.9. Synonymous variants: 196 observed, 197.29 expected, observed/expected ratio (o/e) 0.99, 90% interval 0.88 to 1.12.
Homologues: Orthologues: chimpanzee ST6GAL1 (99% identical), macaque ST6GAL1 (98% identical), rabbit ST6GAL1 (90% identical), dog ST6GAL1 (89% identical), pig ST6GAL1 (89% identical), guinea pig ST6GAL1 (84% identical), mouse St6gal1 (80% identical), zebrafish st6gal1 (47% identical), tropical clawed frog st6gal1 (45% identical), rat St6gal1 (41% identical). Paralogues in human: ST6GAL2 (40% identical), ST3GAL1 (18% identical), ST3GAL4 (18% identical), ST6GALNAC1 (17% identical), ST6GALNAC2 (17% identical), ST3GAL3 (16% identical), ST3GAL5 (16% identical), ST3GAL2 (15% identical), ST6GALNAC4 (14% identical), ST6GALNAC5 (14% identical), ST3GAL6 (13% identical), ST6GALNAC3 (12% identical), and 2 more.
Diseases named in the same sentence as ST6GAL1 in open-access papers:
ST6GAL1 is named in the same sentence as 127 diseases in open-access papers, as found by Europe PMC text mining. Sharing a sentence is not in itself a finding about the gene and the disease. The quoted sentences say what the papers report.
ovarian carcinoma (37 papers, 2008 to 2025). A malignant neoplasm originating from the surface ovarian epithelium. "Of the over 20 human sialyltransferases identified, heightened expression of Golgi β-Galactoside α-2,6-Sialyltransferase 1 (ST6Gal1) appears to be linked to various cancers, including ovarian cancer." (PMID 38515194, 2024). "Similarly, the post-translational modification of fibroblast growth factor receptors (FGFR) via ST6Gal-1 promotes cancer progression and malignancy and underlies the drug resistance in epithelial ovarian cancer." (PMID 37894470, 2023). "ST6GAL1 has been reported earlier to be associated which enhanced growth, survival and metastasis in multiple cancers (including pancreatic, prostate, breast and ovarian cancer)." (PMID 36289103, 2022). "In PDAC, prostate, breast, and ovarian cancers, ST6GAL1 enhances tumor invasiveness and worsens prognosis." (PMID 40860122, 2025). "ST6GAL1 modulates intracellular signaling to regulate tumor cell phenotype, in particular, ST6Gal-I upregulation in ovarian cancer cells seems to confer a cancer stem-like cell (CSC) phenotype." (PMID 38515194, 2024). "ST6GAL1 is known to promote growth, survival, and metastasis, and it is upregulated in various types of cancer (including pancreatic, prostate, breast, and ovarian cancer), while being downregulated in hepatocellular carcinoma." (PMID 39290304, 2024). "A mechanism for upregulated ST6Gal-I expression in ovarian cancer has recently been suggested whereby SOX2 and ST6GAL1 are coordinately amplified in cancer cells, with the Sox2 protein then binding the ST6GAL1 promoter to further augment ST6Gal-I expression." (PMID 38515194, 2024). "In ovarian cancer, regulated by the P120 canonical pathway, adhesion of cancer cells to the peritoneal mesothelium stimulates ST6Gal1 expression facilitating hypersialylation of β1-integrin and elevation of P-cadherin." (PMID 36106023, 2022). "In contrast to the protumorigenic role of ST6GAL1 in pancreatic and ovarian cancers (among others), prior reports suggested that ST6GAL1 is suppressed and plays a tumor-suppressive role in GBM." (PMID 36345944, 2022). "A comparable investigation in ovarian cancer showed that elevation of ST6Gal1 led to P-cadherin enrichment that resulted in upregulation of β1-integrin and drove metastasis via p70 S6 kinase activity." (PMID 36106023, 2022). "According to Dorsett and colleagues the TF SOX2 promotes the expression of ST6GAL1 in ovarian cancer cells by binding a region proximal to the P3 promoter." (PMID 33921986, 2021). "We first analyzed The Cancer Genome Atlas (TCGA) databases for copy number alterations in SOX2 and ST6GAL1 and showed that these two genes are coordinately amplified in patient specimens across a wide range of cancer types, including ovarian cancer." (PMID 31610800, 2019). "In another study, ST6Gal-1 has been reported to regulate stemness and gemcitabine resistance in pancreatic and ovarian cancer by modulating SOX9 and SLUG expression." (PMID 30466404, 2018). "In conclusion, these results indicate that the disruption of B3GNT5 and the corresponding loss of α2-6 sialylation on N-glycans appear due to the preferential silencing of ST6GAL1 gene expression in both ovarian cancer cell lines, IGROV1 and SKOV3." (PMID 28358117, 2017). "ST6Gal1 also blocks cisplatin-induced cell death by reducing the activation of caspase 3 in ovarian cancer." (PMID 28546799, 2017). "Interestingly, ST6GAL1 improves both oxidative and glycolytic pathways in ovarian cancer cells under hypoxia, thus sustaining the overall fitness of ovarian cancer even under stressed conditions." (PMID 40885395, 2025). "ST6GAL1 is upregulated in many malignancies including ovarian cancer." (PMID 37660914, 2023).
ovarian carcinoma (continued). "Similar to these studies in colon cancer models, cell adhesion in the HCC cell line H22 via α5β1 integrin required α2,6 sialylation and ST6Gal1-mediated hypersialylation of integrin β1 resulting in increased attachment to collagen I was determined in ovarian carcinoma." (PMID 36106023, 2022). "In the ovarian cancer models, the ST6Gal1/integrin-mediated signals imparted an invasive phenotype." (PMID 36106023, 2022). "ST6GAL1 might have a prognostic role in ovarian carcinoma, where its increased expression correlates with reduced patient survival." (PMID 33921986, 2021). "Additionally, in pancreatic and ovarian cancer cells, ST6GAL-1 has been shown to induce the expression of CSC-specific TFs, such as Sox9 and Slug." (PMID 32927726, 2020). "To address this hypothesis, we first determined which ST6GAL1 promoter was the primary driver of ST6Gal-I expression in ovarian cancer cells." (PMID 31610800, 2019). "Similarly, previous studies indicated that ST6GAL1 regulates glycolysis in ovarian cancer." (PMID 38212768, 2024). "EGFR could be activated by ST6GAL1, turning out to be a substrate of ST6GAL1 in ovarian cancer." (PMID 31096997, 2019). "The pancreatic cancer cell lines, MiaPaCa-2, S2-LM7AA, and S2-013, as well as the ovarian cancer cell lines, OVCAR-3 and OVCAR-5, have substantial ST6GAL1 expression, typical of most cancer cells." (PMID 37660914, 2023). "To elucidate the molecular pathways by which ST6GAL1 regulates EGFR activation, we performed mechanistic studies using the three ovarian cancer cell lines, OV4, OVCAR-3, and OVCAR-5." (PMID 37660914, 2023). "In the BxPC3 pancreatic cancer line and the ovarian cancer cell line OV4, ST6Gal1 was also identified to provide protection against serum starvation via AKT signaling." (PMID 36106023, 2022). "A recent study showed that ST6GAL1 overexpression induces α-2,6-sialylation of FGFR1 and that high levels of ST6GAL1 decrease the anticancer effect of the FGFR1 inhibitor PD173047 in ovarian cancer cells." (PMID 33921986, 2021). "In another, the glycosyltransferase ST6Gal-1 was shown to regulate stem cell transcription factors, confer CSC phenotype, and promote gemcitabine resistance in pancreatic and ovarian cancer." (PMID 30466404, 2018). "Specifically, ST6GAL1 can mediate resistance to chemoradiation in rectal cancer, the sensitivity of gastric cancer cells to trastuzumab, and resistance to the EGFR inhibitor, gefitinib, in ovarian cancer." (PMID 39272811, 2024). "Furthermore, in the ovarian cancer line OVCAR4, ST6Gal1-mediated α2,6 sialylation was essential for integrin α2-dependent cancer cell survival." (PMID 36106023, 2022). "There is ample evidence that underscores ST6Gal1-mediated expression and α2,6 sialylation of β1-integrin in mammary cancer, HCC, gliomas, ovarian cancer, CRC and even in adipogenesis." (PMID 36106023, 2022). "In ovarian cancer cells, α-2,6 sialylation of fibroblast growth factor receptor 1 (FGFR1) by ST6GAL1 activated the extracellular signaling-regulated protein kinase 1/2 (ERK1/2) and focal adhesion kinase (FAK) pathway, enhancing cell migration and drug chemoresistance." (PMID 33921986, 2021). "Furthermore, the ovarian cancer cell lines within the NCI-60 panel showed a clear correlation between SOX2 and ST6GAL1 CNGs." (PMID 31610800, 2019). "Similarly, ST6Gal1 is reported to directly α2,6 sialylate TNFR1 and block the TNFα-induced apoptotic pathway in macrophages, rectal cancer, and pancreatic and ovarian cancer." (PMID 36106023, 2022). "Since then, ST6Gal1-mediated activation of EGFR has been identified to influence survival, proliferation, apoptosis evasion, chemotherapy resistance, invasion and metastasis in a host of cancers including colorectal cancer ovarian cancer, and pancreatic ductal adenocarcinoma." (PMID 36106023, 2022).
ovarian carcinoma (continued). "ST6GAL1 exerted a similar effect on tumor necrosis factor (TNF)-induced cell death by sialylation of the TNF receptor 1 (TNFR1), which inhibits its internalization, preventing the induction of apoptosis and promoting cell survival in pancreatic and ovarian cancer cells." (PMID 33921986, 2021).
colon carcinoma (32 papers, 2008 to 2025). "As shown, the sialylation of the EGFR affects EGFR-mediated cell growth and reduces sensitivity to gefitinib in human colon cancer cells, whereas the anticancer effect of gefitinib was augmented in ST6Gal-1-deficient cells." (PMID 37894470, 2023). "Earlier studies in colon cancer cell models suggested that variable functional ST6GAL1 in exosomes released by tumor cells are linked to the source cells." (PMID 35676533, 2022). "Increased sialylation of integrin β1 through alpha-2,6-sialyltransferase 1 (ST6GAL1) in colon cancer cells was associated with cancer progression by promoting cell motility and attachment to collagen I and laminin." (PMID 34646995, 2021). "The anticancer effect of the EGFR kinase inhibitor, gefitinib, has been shown to be increased in ST6Gal1-deficient colon cancer cells." (PMID 30187356, 2018). "The anticancer activity of a chemotherapeutic tyrosine kinase inhibitor, gefitinib (Iressa®), is augmented in ST6Gal1-deficient colon cancer cells." (PMID 30187356, 2018). "α2,6-sialylation by ST6Gal1 is expressed in colon cancer tissues compared to that of normal tissue and expression of ST6Gal1 is correlated to the high risk group in pediatric acute leukemia." (PMID 24589677, 2014). "Importantly, the anticancer effect of the EGFR kinase inhibitor, gefitinib, was increased in ST6Gal1-deficient colon cancer cells." (PMID 30187356, 2018). "ST6Gal1 is up-regulated in colon carcinoma, and its metastasis and poor prognosis are ascribed to sialylation of the Fas death receptor by ST6Gal1 that protects Fas-mediated apoptosis." (PMID 38958800, 2024). "Conversely, ST6GAL1 was OE in the OV4 ovarian, and SW48 colon cancer lines, which have unusually low levels of endogenous ST6GAL1." (PMID 37660914, 2023). "A recent study has elegantly demonstrated that tumor cells secrete ST6GAL1 in exosome vesicles or exomere smaller particles and are capable of transferring into the recipient cell as a functional ST6GAL1 in colon cancer cell models." (PMID 35676533, 2022). "More specifically, sialylation by ST6Gal1 of Fas hindered subsequent death complex formation and prevented internalization of Fas receptor, abrogating Fas-mediated apoptosis in colon cancer cells." (PMID 36106023, 2022). "This hints towards a more nuanced function of ST6Gal1-AKT axis in colon cancer even though a pattern of ST6Gal1-mediated increases in PI3K/AKT signaling was often observed." (PMID 36106023, 2022). "ST6Gal1-mediated hypersialylation of β1 integrin in colon cancer cells also resulted in enhanced fibronectin binding that promoted survival via activation of a downstream cascade involving paxillin and AKT." (PMID 36106023, 2022). "In a colon cancer model, Swindall and colleagues identified the Fas receptor (FasR) as an ST6GAL1 substrate." (PMID 33921986, 2021). "ST6GAL1-mediated sialylation of FasR blocked Fas internalization and the formation of the death-inducing signaling complex, disabling apoptotic signaling in colon cancer cells." (PMID 33921986, 2021). "In colon cancer cells, silencing of ST6GAL1 increased the anti-cancer effect of the EGFR inhibitor gefitinib, whereas ST6GAL1 overexpression decreased the cytotoxic effect of gefitinib." (PMID 33921986, 2021). "ST6GAL-1 transfers α2-6-linked sialic acids to substrate proteins and its expression is enriched in CD133+/ALDH+, irinotecan-resistant colon cancer cells." (PMID 32927726, 2020). "A recent study provided evidence that ST6Gal-1, a sialyltransferase that adds sialic acid residues to the N-glycans of certain membrane receptors, is a marker of colon cancer stem cells." (PMID 29652830, 2018). "ST6Gal1-induced α2,6 sialylation has been shown to be critical for adhesion and migration of colon cancer cells." (PMID 30187356, 2018). "Functional ST6Gal1 on EGFR has been shown to be highly correlated with colon cancer progression and metastasis." (PMID 30187356, 2018).
colon carcinoma (continued). "In addition, colon cancer exosomes encapsulating ST6GAL1 that can be delivered to target cells and involved in cell signaling have been reported recently." (PMID 35676533, 2022). "ST6Gal1 sialylation of β1 integrin in colon cancer also enhanced radio-resistance." (PMID 36106023, 2022). "For example, sialyltransferase ST6Gal1, which adds the negatively charged sugar, sialic acid, to an α2,6 linkage at the terminal N-glycan, is overexpressed in many types of cancers such as colon cancer." (PMID 28032597, 2017). "Moreover, upregulation of ST6Gal1 is correlated with increased metastatic potential and poor prognosis in colon cancer as well as in other solid tumors." (PMID 28032597, 2017). "Furthermore in vitro studies have shown that ST6GAL1 upregulation promotes cell migration and invasion through its interaction with the B1 integrin receptor, while animal models of colon cancer implicate ST6GAL1 in tumor invasiveness." (PMID 25465919, 2014). "To investigate the effects of ST6GAL1-mediated sialylation on EGFR activity, we assessed EGFR activation in pancreatic, ovarian, and colon cancer cell lines in which ST6GAL1 expression was directly modulated." (PMID 37660914, 2023). "In the present study, we report that ST6GAL1-mediated sialylation activates EGFR in seven different cancer cell models including ovarian, pancreatic, and colon cancer cells." (PMID 37660914, 2023). "When the colon cancer cell line HCT116 was treated with nano-diamino-tetrac (NDAT), an antiproliferative/angiogenic agent, the protein expression of ST6Gal1 along with phospho-PI3K was diminished." (PMID 36106023, 2022). "Experiments on the selection of colon cancer cells according to chemosensitivity showed that chemoresistant cells are enriched in both ALDH1-positive and ST6Gal-1-expressing cells." (PMID 29652830, 2018). "Surprisingly, in view of the very different cell types, we found that US7 cells with ST6Gal1 overexpression had 19 genes in common (18 increased and one decreased) with the SW948 ST6Gal1 overexpressing colon cancer cells, including, among others, ST6GAL1, TGFβ2, and CTF1." (PMID 35371997, 2022). "Others have shown that decreased ST6Gal1 may increase EGF-induced EGFR phosphorylation and ERK1/2 activation in colon cancer cells." (PMID 30187356, 2018). "We previously reported that ST6GAL1 sialylates and activates EGFR in PDAC, ovarian, and colon cancer cell lines, as well as in nonmalignant cells, although an inhibitory effect of sialylation has also been reported." (PMID 37643018, 2023).